LINC00320 (long independently transcribed non-coding RNA 320)
Synonyms: PRED14; FLJ37539; C21orf131; NCRNA00320
Gene: Long non-coding RNA gene on chromosome 21 (20,651,450 to 20,803,816, reverse strand). Ensembl gene ENSG00000224924.
Diseases named in the same sentence as LINC00320 in open-access papers:
LINC00320 is named in the same sentence as 2 diseases in open-access papers, as found by Europe PMC text mining. Sharing a sentence is not in itself a finding about the gene and the disease.
LINC00320 shares sentences with these, for which no sentence is quoted: epilepsy (1 paper); glioma (1).